RNU1-76P (RNA, U1 small nuclear 76, pseudogene)
Gene: Small nuclear RNA gene on chromosome 5 (7,980,146 to 7,980,304, forward strand). Ensembl gene ENSG00000199773.
Homologues: Orthologues: chimpanzee U1 (99% identical), macaque U1 (92% identical), dog U1 (75% identical), rat LOC120102046 (69% identical), rat LOC120103213 (69% identical), mouse Gm23405 (67% identical), guinea pig U1 (66% identical). Paralogues in human: RNU1-89P (86% identical), RNU1-1 (84% identical), RNU1-2 (84% identical), RNU1-27P (84% identical), RNU1-28P (84% identical), RNU1-3 (84% identical), RNU1-4 (84% identical), RNVU1-18 (84% identical), RNVU1-29 (84% identical), U1 (84% identical), RNU1-39P (84% identical), RNVU1-28 (84% identical), and 134 more.